IL6 (interleukin 6)
Diseases named in the same sentence as IL6 in open-access papers (continued):
Sharing a sentence is not in itself a finding about the gene and the disease.
heart failure (continued). "IL-6 acts on the various cell types that are involved in heart failure." (PMID 35878343, 2022). "Interestingly, several paracrine factors relevant in the pathophysiology of heart failure, including IL6, IL10, NPPA and NPPB, were also expressed at higher levels in SSEA4+CD34- cells." (PMID 35709180, 2022). "TNF-α, IL-1 and IL-6 are among the pro-inflammatory cytokines that are increased in heart failure." (PMID 36547425, 2022). "The presence of pro-inflammatory cytokines, such as TNF-α, IL-1, and IL-6, that may contribute to the pathogenesis of cardiac remodeling, and to systolic and diastolic dysfunction, is frequently described in human heart failure." (PMID 35878343, 2022). "IL-6 is consistently upregulated in experimental models of cardiac injury and heart failure regardless of the underlying etiology and is expressed by cardiomyocytes, infiltrating mononuclear cells, and fibroblasts." (PMID 35035498, 2022). "It was established that cytokines such as TNF-α, IL-1β, and IL-6 play an important role in the development of heart failure in several clinical scenarios, and some attempts were even made to regulate their effects on heart tissue, yet no conclusive treatment proposals were established." (PMID 35269577, 2022). "The concentrations of IL-5, IL-6 and IL-9 were significantly higher in the saliva of heart failure patients with both NS and HS compared to the control group, while IL-4 level was significantly higher only in heart failure patients with HS." (PMID 36300113, 2022). "Further, inhibition of JAK1 may promote myocardial fibrosis, infarction, and malignant arrhythmia through activation of the interleukin 6 (IL-6) heart failure pathway." (PMID 36365202, 2022). "Elevated levels of IL-6 are correlated with cardiac damage and heart failure in rodent models." (PMID 35036128, 2021). "Finally, IL-6 and adiponectin levels correlated most strongly with parameters of heart failure severity, particularly BNP." (PMID 34685378, 2021). "These molecular events have been associated with the progression of this pathophysiology, via Fas (sFas), Fas ligand (sFas-L), TNFα (tumor necrosis factor α), and IL-6 (interleukin-6), which are negatively correlated with fractional shortening and result in heart failure." (PMID 34445422, 2021). "The damage, repair and remodeling of myocardium are the important link in the occurrence and development of heart failure, of which immune/inflammatory cells (neutrophils, lymphocytes, etc.)and the inflammatory factors (tumor necrosis factor, interleukin-6, etc.)released by them are involved." (PMID 34869661, 2021). "It has been reported that the levels of IL-6, CRP, and TNF-α are important indicators of MI-related cardiac complications, and these inflammatory cytokines have been reported to be closely associated with the occurrence of heart failure." (PMID 34123595, 2021). "IL-6 levels have been reported as predictors of mortality in acute HF and acute coronary syndromes as well as severe chronic HF in some studies, but data on ambulatory elderly patients with heart failure are scarce in the current literature." (PMID 33535417, 2021). "IL‐6 is consistently upregulated in experimental models of cardiac injury and heart failure regardless of the underlying aetiology and is expressed by cardiomyocytes, infiltrating mononuclear cells and fibroblasts." (PMID 34773379, 2021). "In addition, IL‐6 level has also been reported to be an independent biomarker for atrial fibrillation, in patients with heart failure displaying significantly higher concentrations." (PMID 33124775, 2020). "It is believed that high concentration of IL-6 can lead at least partially to the development of heart failure and may serve as an indicator of worse prognosis in patients with cardiovascular diseases." (PMID 33036382, 2020).
heart failure (continued). "Because the plasma level of IL-6 in the patients with heart failure was related to its severity, severe pressure overload (sTAC) may increase the level of Il6 mRNA in mouse failing hearts." (PMID 31931613, 2020). "Pro-BNP and IL-6 are usually used to index heart failure in clinical studies." (PMID 32075047, 2020). "TNF and IL-6 serum levels correlate with heart failure severity and prognosis." (PMID 33344515, 2020). "Our findings suggest that cardiac chagasic patients have an increased percentage of inflammatory monocytes and produce more IL-6, a biomarker of heart failure and left ventricular dysfunction, whereas asymptomatic chagasic individuals present a higher percentage of reparative monocytes and CCL17." (PMID 31379862, 2019). "However, recently it was reported that circulating pro-inflammatory cytokines TNF-α and IL-6 decreased significantly after 3 months of PD and remained low at 6 months of follow-up in patients with heart failure undergoing PD due to overflow." (PMID 31612137, 2019). "Others have reported an association between IF biomarkers and LVDD in patients with symptomatic heart failure, and studies on animal models showed that pathological elevations of IL-6 result in extensive cardiac fibrosis, by regulating cell function through a cell surface receptor." (PMID 31275453, 2019). "Recent studies have found associations between IL-6 level and CAD severity, all-cause and cardiovascular mortality in patients with CAD, long-term cardiovascular mortality in patients with ST-segment elevation MI, and progression to heart failure." (PMID 31739518, 2019). "Considering the dilated cardiomyopathy (DCM) as a relatively high-incident disease leading to heart failure, the aim of this study is to determine the difference in the expression level of interleukin (IL)-6 and IL-18 in patients with ischemic and idiopathic DCM." (PMID 31384408, 2019). "Increased levels of IL-1β and IL-6 in RVs from SuH mice indicate the installation of a pro-inflammatory environment in the myocardium, and it has been described that these cytokines are involved with development of heart failure." (PMID 30574088, 2018). "Additionally, multiple studies have shown high levels of pro-inflammatory cytokines such as TNF-α, IL-6, and IL-1β in the peripheral circulation and heart of cardiac failure patients." (PMID 30558188, 2018). "Interleukin-6 stimulates cardiomyocyte hypertrophy and apoptosis and may contribute to fibrosis during heart failure thereby altering cardiac conduction and contributing to AF." (PMID 30071583, 2018). "Similarly, IL-6 and C-reactive protein were reduced following Hatha yoga intervention in heart failure patients, which represent another clinical population with a high baseline inflammatory burden, compared to controls." (PMID 28694775, 2017). "Heart failure is a complex molecular disease process involving more than IL-6 and MYLK." (PMID 27884156, 2016). "However, systemic inflammation can also develop in response to sterile insults and high levels of cytokines can be found in blood even after cardiac failure, as confirmed by our own data on interleukin-6." (PMID 25757508, 2015). "Of these molecules, CTGF and IL-6 are considered among the markers of heart failure." (PMID 25997003, 2015). "It has became evident that heart failure is associated with subclinical inflammation which is in agreement with study demonstrating non-specific elevation in levels of some proinflamatory markers, such CRP, TNF-alfa, Il-6." (PMID 25400332, 2014). "Interestingly, the myocardial IL-6 expression decreases, whereas the circulating level of IL-6 was increased in patients with heart failure." (PMID 22675647, 2012). "Therefore, reducing levels of CRP, TNF-α, and IL-6 in heart failure patients may help to reduce heart failure symptoms and improve the overall health of heart failure patients." (PMID 41179565, 2025).
heart failure (continued). "In addition, the activation of p38 via MKK6bE may mediate the inflammatory induction of TNF-α and IL-6 in cardiomyocytes and contribute to the development of fibrosis, adverse cardiac remodeling, and heart failure." (PMID 40610735, 2025). "Studies have shown that patients with decompensated heart failure (HF) have higher LPS concentrations compared to those with stable HF, and the progression of HF is associated with an increase in inflammatory markers such as soluble (s) CD14, tumor necrosis factor (TNF)α, and interleukin 6 (IL-6)." (PMID 40766948, 2025). "In particular, interleukin 6 (IL-6) has a central role in both initiation and perpetuation of low-grade inflammation, and could be a useful biomarker to improve preoperative risk stratification for PMI and heart failure." (PMID 40491666, 2025). "It is thought that elevated IL-6 levels may play a role in the initial stages of heart failure." (PMID 38338960, 2024). "Accordingly, an increment in the pro-inflammatory cytokine concentrations, similar to interleukin 6 (IL-6) and tumor necrosis factor, occurs, thereby impairing both renal and myocardial functions, which, in turn, leads to the speeding up of the progression of heart failure (HF)." (PMID 37529809, 2023). "Although monocytes are considered an essential component of the inflammatory cascade in heart failure, relevant evidence until now has been based mainly on studies regarding monocyte-derived cytokines implicated in the pathogenesis of heart failures, such as TNF and IL-6." (PMID 37189647, 2023). "Moreover, it will be of interest whether SGLT-2-inhibitors reduce Interleukin-6 in non-heart-failure populations as well, e.g., in chronic kidney disease." (PMID 37445494, 2023). "Consequently, IL-6 and TNF-α are associated with heart failure and all-cause mortality." (PMID 36729923, 2023). "Moreover, higher mortality was observed in stable heart failure patients with elevated IL-6." (PMID 37373960, 2023). "IL-6 acts as a critical marker of inflammation as well as a feature of aging and plays a role in the pathophysiological mechanisms driving age-related diseases (e.g., osteoporosis, heart failure, AD, the decline in cognitive performance, and community-acquired pneumonia requiring hospitalization)." (PMID 35935995, 2022). "Although IL-6 has been associated with the infarct size and cardiac function of STEMI patients and in a large cohort of heart failure patients, such studies associating IL-6 could not conclude the causality." (PMID 35163735, 2022). "Inflammatory activity may be one potential mechanism, given that research shows that heart failure patients have higher levels of proinflammatory cytokines as compared to healthy controls and pro-inflammatory cytokines, such as IL-6 and TNF-alpha, have been identified as prognostic markers in HF." (PMID 35271674, 2022). "On the other hand, aspirin could reduce TNF-α and IL-6 levels in patients with heart failure." (PMID 33969115, 2021). "Indeed, by inducing an anti-apoptotic program and reducing long-term contractility, the excessive IL-6 secretion may finally lead to adverse LV remodeling and heart failure." (PMID 33507957, 2021). "The presence of chronic diseases, such as heart failure, and surgical procedures additionally contribute to the stimulation of the immune and sympathetic systems, causing inflammation manifested by high levels of C-reactive protein (CRP), elevated white blood cell count, and interleukin 6 (IL-6)." (PMID 32273868, 2020). "Finally, physical training programs implementations in patients destined for activity restriction such as heart failure resulted in decreased circulatory concentrations of proinflammatory cytokines including plasma TNF-a and IL-6, both implicated in preterm labor." (PMID 29889906, 2018). "Therefore, one can speculate that our findings suggest that IL-6 may also be an important contributor to IKr reduction in heart failure." (PMID 30521586, 2018).
heart failure (continued). "Circulating IL-6 levels were increased in RV failure on acutely increased afterload, which also probably contributes to the perpetuation of the inflammatory state and to the acceleration of the progression of global heart failure (as already described in the setting of LV failure)." (PMID 30177883, 2018). "Moreover, in a heart failure cohort soluble glycoprotein 130 (sgp130) levels were associated with mortality, whereas plasma IL-6 was not." (PMID 27936014, 2016). "Evidence that IL-6 blockade is unlikely to cause short-term increases in NT-proBNP, which might be a signal for heart failure risk, in these patients is also reassuring." (PMID 27744141, 2016). "Compared to control group, six-minute walking test (6-MWT) distance was longer, and Minnesota Living with Heart Failure Questionnaire (MLHFQ) score and levels of inflammatory markers (IL-6, TNF-α, and hs-CRP) were lower in the study group (all p < 0.05)." (PMID 42058421, 2026). "IL-6, elevated in both OSAS and heart failure, modulates sodium channel availability and reduces gap junction coupling through connexin-43 downregulation, contributing to conduction abnormalities and increased arrhythmogenic substrate." (PMID 41011065, 2025). "As heart failure progresses, pronounced inflammatory responses, such as the overproduction of TNF-α and IL-6, result in damage to the vascular walls and reduced myocardial efficiency." (PMID 39805484, 2025). "Variables were selected from 13 candidate factors (age, mechanical ventilation, nutritional status, comorbid respiratory failure, comorbid heart failure, pulmonary rales, pulmonary rhonchi, PLT, CRP, PCT, IL-6, IgA, and IgM)." (PMID 41234411, 2025). "Studies suggest that omega-3 supplementation effectively lowers circulating levels of inflammatory cytokines, particularly in patients with heart failure (HF), by reducing TNF-α, IL-6, and C-reactive protein (CRP) levels." (PMID 40427653, 2025). "This meta-analysis confirms that systemic inflammation—reflected by elevated IL-6, hs-CRP, and NLR—is a strong and independent predictor of mortality and adverse outcomes in heart failure." (PMID 41375916, 2025). "Dapagliflozin increased serum GSH-Px and SOD levels and decreased IL-1β, IL-6, TNF-α and MDA levels (P < 0.05) in a rabbit model of heart failure." (PMID 39874368, 2025). "The increase of IL-6 content can promote the apoptosis of cardiomyocytes, and TNF-α is an important index reflecting the degree of heart failure." (PMID 39874368, 2025). "Elevated levels of pro-inflammatory cytokines such as interleukin-6 and chemokine ligand 1 suggest a systemic inflammatory response, which may contribute to the progression from transient myocardial dysfunction to chronic remodeling or even heart failure in some patients." (PMID 41227032, 2025). "Several studies have reported that n–3 PUFA supplementation reduces inflammatory markers in patients with heart failure, including TNF-α, IL–1, and IL–6." (PMID 39805484, 2025). "The inflammatory cytokine levels (IL-1, IL-6, and TNF-α) are significantly higher in heart failure patients compared to the control group (p < 0.001 for all markers)." (PMID 40943854, 2025). "This study demonstrates that IL-1, IL-6, and TNF-α are significantly elevated in heart failure patients and strongly correlate with reduced LVEF, indicating their association with disease severity." (PMID 40943854, 2025). "Multiple randomized clinical trials and observational studies have shown that an omega-3 supplementation significantly reduces inflammatory biomarkers such as C-reactive protein (CRP), IL-6, and TNF-α in patients with CKD and heart failure." (PMID 40806569, 2025). "Simultaneously, in the insulin-resistant state of heart failure patients, the production of inflammatory factors such as tumor necrosis factor-alpha (TNF-α) and interleukin-6 (IL-6) increases." (PMID 40442740, 2025).
heart failure (continued). "Compared with HF group, IL-1β, IL-6 and TNF-α inflammatory factors in blood of rabbits with heart failure were decreased in different degrees after administration of dapagliflozin, and there were significant differences (P<0.05)." (PMID 39874368, 2025). "Previous studies have shown that a large number of inflammatory factors such as IL-6 and TNF-α are expressed in the serum of patients with heart failure." (PMID 39874368, 2025). "Interleukin-6 (IL-6), tumor necrosis factor-α (TNF-α), and CRP have been reported as serum inflammatory markers for heart failure." (PMID 39026227, 2024). "This is attributed to the release of various cytokines, such as IL-1α, IL-1β, IL-6, and TNF-α, which negatively affect myocardial healing and contribute to the development of heart failure." (PMID 38667586, 2024). "Compared to tercile 1, participants with IL-6 tercile 3 had a higher adjusted risk of and all-cause mortality (HR: 1.98 [95% CI: 1.67-2.36]), CV mortality (HR: 1.55 [95% CI: 1.05-2.30]), non-CV mortality (HR: 2.05 [95% CI: 1.65-2.56]), and heart failure (HR: 1.48 [95% CI: 0.99-2.19])." (PMID 39077632, 2024). "Plasma levels of IL-6 increase with the severity of chronic heart failure and can – independently of LVEF levels – be prognostic for heart failure patients, showing the importance of this cytokine in the pathophysiology of the disease." (PMID 36263604, 2023). "Oncostatin M is part of the interleukin-6 (IL-6) family and regulates remodeling and PTH effects in bone as well as cardiac FGF23 production in heart failure via glycoprotein gp130." (PMID 37225713, 2023). "The depleted NK cell levels in heart failure and advanced CKD have been ascribed to the chronic inflammatory state and upregulation of IL-6 pathways which induces NK cell dysfunction and anergy." (PMID 37189647, 2023). "A growing body of evidence showed that neurohormones and cytokines, including IL-6 and TNF-alpha, contribute to the progression of heart failure." (PMID 35847039, 2022). "However, both animal and human studies have showed that if IL6 signaling remains elevated after the immediate need to preserve the insulted tissue has resolved, reduced contractility of the myocardium induces activation of hypertrophic gene signaling, which can eventually lead to heart failure." (PMID 35884952, 2022). "The first evidence of inflammation in HFpEF came from the observation that heart failure patients have higher levels of circulating inflammatory cytokines such as TNF-α, IL-1, IL-6, IL-8, and monocyte chemotactic protein (MCP)-1." (PMID 36672578, 2022). "The hawthorn treatment group reduced the levels of IL-6, IL-8, IL-1β and TNF-α in cardiomyocytes due to doxorubicin treatment for heart failure (p < 0.01)." (PMID 36140986, 2022). "A growing body of evidence shows that neurohormones and cytokines, including IL-6 and TNF-alpha, contribute to the progression of heart failure." (PMID 35847039, 2022). "In all patients, univariate analysis showed that heart failure, LAD, hs-CRP, IL-6, CITP, and TGF-β1 were connected with Log-LPS." (PMID 36285296, 2022). "Univariate linear regression analyses showed that Log-LPS was correlated with heart failure, LAD, hs-CRP, IL-6, CITP, and TGF-β (P < 0.05)." (PMID 36285296, 2022). "Wnt5a induces IL-6 and TIMP-1 by activation of ERK in CFs, resulting in cardiac inflammation and subsequent heart failure progression." (PMID 34564708, 2021). "To determine the correlation between these levels and severity of heart failure, we analyzed the correlation among serum levels of BNP, IL-6 and sαKl." (PMID 33479413, 2021). "In the present study, sunitinib upregulated TGF-β, IL-1, IL6, IL-8 and CXCL12 both in cardiac cells and human renal adenocarcinoma cells that are involved in cell death and heart failure as well as in cancer cell survival and resistance to apoptosis." (PMID 34178667, 2021).